POMC (proopiomelanocortin)
Diseases named in the same sentence as POMC in open-access papers (continued):
Sharing a sentence is not in itself a finding about the gene and the disease.
Obesity (continued). "The present work, therefore, focuses on the evaluation of the association of clinical markers related to obesity and SNPs of the LEP, LEPR, POMC, PCSK1, and MC4R genes in a healthy Mexican population." (PMID 35741707, 2022). "The same obesity-prone phenotype is shown in mice, when the autophagic process is inhibited in POMC neurons." (PMID 35902579, 2022). "In a previous study, we identified 15 variants in 16 unrelated individuals among 2548 people with severe obesity studied using the same methods and showed they caused an LOF in cells using a POMC reporter assay." (PMID 35137184, 2022). "Setmelanotide (Imcivree) is a melanocortin-4 (MC4) receptor agonist used for the treatment of obesity due to proopiomelanocortin (POMC), proprotein convertase subtilisin/keying type 1 (PCSK1), or leptin receptor (LEPR) deficiency." (PMID 36232301, 2022). "Concerning neuronal responses to diet or obesity, DIO and HFD consumption induced injury and loss of Pro-opiomelanocortin (POMC) neurons in the ARC and Sim1 neurons of the paraventricular nucleus (PVN)." (PMID 35873818, 2022). "An improved understanding of how anorexigenic ARC POMC+ neurons are generated is likely to aid efforts to understand the molecular mechanisms helping to prevent obesity and metabolic syndrome." (PMID 36033614, 2022). "DIO rats fed a chow diet display increased inhibitory inputs to POMC neurons compared to obesity-resistant rats." (PMID 35474338, 2022). "Noteworthy, both constitutive and adult-onset deletion of PC1/3 in POMC-expressing tissues induced obesity, although only mildly and transiently, showing that POMC processing regulates body weight development." (PMID 35963866, 2022). "In summary, although the two neurons did not die of GPX4 reduction, the study focused on only one point of GPX4 and did not delve into other regulators, indicating that there are other pathways affecting the activity of POMC neurons under obesity conditions." (PMID 36479119, 2022). "Second, MFN2 ablation, and as a consequence the lowering of contact sites, severely impairs anorexigenic pro-opiomelanocortin (POMC) processing and increases ER stress, leading to the development of leptin resistance, decreased energy consumption, and obesity." (PMID 35943566, 2022). "Correspondingly, restraining the TNFα/NF-κB pathway in microglia can effectively reduce microglial activation and prevent diet-induced obesity, and blocking the TNFα/NF-κB pathway in POMC neurons can also reduce the diet-induced obesity." (PMID 33826123, 2022). "Together, hyperphagia, the accompanying obesity, and associated comorbidities can contribute to physiologic and psychological impairments and reduced QOL in patients with POMC or LEPR deficiency." (PMID 35123544, 2022). "The aim of our project was to establish the Polish database of severely obese children and adolescents and to evaluate the prevalence of monogenic forms of obesity in this cohort, with a special focus on leptin–proopiomelanocortin pathway abnormalities." (PMID 36479220, 2022). "Specifically, this obesity in driven by hyperphagia when the BBSome is disrupted in POMC neurons, and these mice were glucose intolerant and insulin resistant." (PMID 36568981, 2022). "Here, we find that deletion of PC1/3 in obesity-related neuronal cells expressing proopiomelanocortin mildly and transiently change body weight and fail to produce a phenotype when targeted to Agouti-related peptide- or nestin-expressing tissues." (PMID 35963866, 2022). "The knockout of apoptosis-inducing factor (AIF) in POMC neurons can increase fatty acid utilization and reverse mitochondrial dynamics, improving systemic glucose metabolism in obesity." (PMID 39871928, 2022). "A role for genetic variation in or near the POMC locus as a determinant of obesity or obesity-related quantitative traits in the general population has been reported." (PMID 35207755, 2022).
Obesity (continued). "In the context of the hypothalamus, the specific modulation of macroautophagy and autophagy-related genes in POMC neurons modulates obesity and conduces metabolic disorders and insulin resistance." (PMID 35326371, 2022). "In contrast, another study that specifically induced the death of AgRP and POMC neurons, profound metabolic disorders and obesity emerged." (PMID 36479119, 2022). "In particular, obese mice present ER stress in POMC neurons and peripheral tissues, suggesting that ER stress is induced by metabolic disorders related with obesity and HFD." (PMID 33849593, 2021). "Rodents with Socs3 deletion in proopiomelanocortin (POMC) neurons are resistant to diet‐induced obesity and have lower levels of circulating leptin." (PMID 34057306, 2021). "The role of 5-HTR2C in POMC neurons and the new role in neural circuits suggest that the new anti-obesity drugs act directly on the CNS, thereby reducing the negative effects caused by acting on the periphery, which will be discussed in the future." (PMID 34367066, 2021). "POMC activation reduces food intake through the release of α-MSH, and Pomc-deficient mice in the ARC (ArcPomc−/−) showed obesity and hyperphagia." (PMID 33810547, 2021). "Together, these data support a model in which a fed signal in POMC neurons abrogates HFD-induced obesity." (PMID 34549728, 2021). "Knockout mice for POMC or MC4R are hyperphagic and obese and, in humans, mutations in the POMC and MC4R genes produce severe obesity." (PMID 34068091, 2021). "Mutation of the STAT3-recruiting tyrosine 1138 on the LepRb prevented SOCS3 feedback inhibition of leptin signalling, while overexpression of a constitutively active version of STAT3 in POMC neurons elevated Socs3 expression and led to obesity." (PMID 34502119, 2021). "In the hypothalamus, SIRT1 has been revealed as an attractive target against obesity and type 2 diabetes in both POMC and SF1 neurons." (PMID 34201257, 2021). "We have previously investigated the contribution of NPY and POMC systems in obesity-induced hypertension and activation of RSNA in adult rabbits on a 3-week HFD." (PMID 34248679, 2021). "Taken together, these findings support that acupuncture can suppress appetite and alleviate obesity by upregulating the expression of POMC in obese animal models." (PMID 33868169, 2021). "On one hand, the activation of TLR4 signal in AgRP/NPY and POMC neurons decreased the expression of AgRP/NPY and increased the expression of POMC, which induced the reduction of appetite and suggested to be involved in obesity." (PMID 34899611, 2021). "Further, deletion of 5-HT2CRs from POMC neurons leads to hyperphagia and obesity in mice and 5-HT2CRs expressed by POMC neurons partly mediates anorexigenic effects of 5-HT analogs during hunger-driven feeding." (PMID 34290371, 2021). "The removal of Nhlh2 from Kiss1 neurons did not induce any metabolic phenotype in Kiss1Cre:Nhlh2fl/fl mice under regular or HFD chow, which supports a role for Nhlh2 in POMC neurons in the obesity phenotype of whole-body KOs." (PMID 34494548, 2021). "The conditional knockout of Dicer in the mouse brain or in hypothalamic POMC neurons leads to hyperphagic obesity, demonstrating the importance of miRNAs in energy homeostasis." (PMID 34831343, 2021). "Recently, several genes and pathways have been found to participate in the occurrence and advancement of obesity associated type 2 diabetes mellitus, including FGF21, pro-opiomelanocortin (POMC), PI3K/AKT pathway and JAK/STAT pathway." (PMID 33902539, 2021). "The same effect was observed when a S1P agonist (SEW2871) was administered; mice had an induced anorexigenic effect, preventing obesity and associated metabolic diseases in a STAT3/POMC-dependent axis." (PMID 34069652, 2021). "Previous studies have also described metabolic impairments (obesity) in Nhlh2 KO mice due to the decrease in the number of POMC neurons." (PMID 34494548, 2021).
Obesity (continued). "The chromosome 2p22 (a region encompassing the POMC gene) has been identified as the site of gene(s) affecting obesity and obesity-related traits." (PMID 34552557, 2021). "The specific knockdown of Mir7 and knockout of Mir17-Mir92 in POMC neurons aggravated diet-induced obesity in females and males, respectively." (PMID 34526970, 2021). "Compared to the normal tissues, the five obesity-related genes (POMC, LEP, PCSK1, MTCH2, and GPR120) showed a similarity alteration of DNA methylation patterns in different cancer tissues." (PMID 33299884, 2020). "Elevated hypothalamic NPY and decreased POMC are thought to promote the development and maintenance of obesity." (PMID 32545529, 2020). "Deficiency in POMC with consequent inactivation of MC4R by α-MSH reduction causes hyperphagia, severe obesity, and red hair." (PMID 33261141, 2020). "NCOA1L1376P knock-in mice bearing a mutation identified in obese patients show decreased leptin-induced depolarization of POMC neurons, increased food intake, and exacerbated obesity." (PMID 32449767, 2020). "The deletion of MFN2 in anorexigenic POMC neurons impaired ER–mitochondria contacts, resulting in defective POMC processing, ER stress-induced leptin resistance, and obesity." (PMID 33329397, 2020). "The deletion of NCOA1 in POMC neurons attenuates their depolarization by leptin, decreases POMC expression, and increases food intake, which accelerates high-fat diet-induced obesity." (PMID 32449767, 2020). "Diet-induced obesity and T2DM have been associated with a disturbed balance between the anorexigenic POMC and the orexigenic NPY/AgRP neurons." (PMID 32814716, 2020). "The polymorphisms located in the regions of the POMC, DNAJC27 (RBJ), and ADCY3 genes were associated with pubertal development, height, BMI, obesity, and type I diabetes mellitus." (PMID 33552117, 2020). "For example, emerging data suggest that the POMC promoter, which is critical for hypothalamic leptin signaling, is highly methylated in obesity." (PMID 32407841, 2020). "Interesting novel developments are clinical trials with MC4R-agonists in patients with leptin-melanocortin pathway deficiencies, e.g. POMC and LEPR deficiency, and glucagon-like peptide 1 (GLP-1) agonists for adolescents with obesity." (PMID 32384097, 2020). "For instance, the constitutive expression of XBP1 in POMC neurons was shown to protect the neurons against diet-induced obesity and also improved insulin sensitivity." (PMID 33329397, 2020). "Compared to the normal tissues, five obesity-related genes (POMC, LEP, PCSK1, MTCH2, and GPR120) did show a similarity alteration of DNA methylation patterns in different cancer tissues." (PMID 33299884, 2020). "Studies of proopiomelanocortin (POMC) mutations showed an association between obesity in humans and a subsequent increase in the risk of obesity-related diseases, such as T1D and T2D." (PMID 33113859, 2020). "Together, these data suggest that POMC neuron-specific ablation of Sh2b1 is insufficient to induce obesity and metabolic disease." (PMID 32251290, 2020). "Deletion of Mfn2 in POMC neurons disrupted proper mitochondrial–ER homeostasis, and led to reduced energy expenditure, leptin resistance, and obesity." (PMID 33339212, 2020). "In this context, pro-opiomelanocortin (POMC)-expressing neurons located into the hypothalamic arcuate nucleus (ARC) are critically involved in leptin’s effects on glucose homeostasis in obesity and insulin resistance states." (PMID 33192583, 2020). "Severe insulin resistance can occur in the setting of severe obesity syndromes resulting from pathogenic variants in MC4R, POMC, LEP, and LEPR." (PMID 33210059, 2020). "Here, the authors show that inhibition of ciliogenesis in POMC neurons during development results in lysosomal protein degradation-dependent axonal disruption and adult obesity in mice." (PMID 33188191, 2020).
Obesity (continued). "Because the sympathoexcitatory response to insulin depends on α-MSH in the PVN, this result indirectly suggests that insulin’s activation of ArcN POMC neurons is also weakened with obesity in females." (PMID 32160920, 2020). "On the other hand, the depletion of SIRT6 in a neuron-specific manner lowered plasma growth hormone (GH)/insulin-like growth factor-1 (IGF-1) levels and decreased hypothalamic POMC expression, which led to postnatal growth retardation and obesity." (PMID 32143417, 2020). "Genetic defects in the POMC gene leads to early-onset obesity with hyperphagia, which is thought to be a result of inadequate production of both α- and β-MSH." (PMID 33144604, 2020). "As observed in POMC deficiency, genetic alterations in BDNF in humans is linked to elevated food intake and obesity." (PMID 32166324, 2020). "Even moderate overexpression of ARC NPY, and likely underexpression of POMC, is sufficient to induce overfeeding and obesity." (PMID 33138074, 2020). "Hyper-methylation of Leptin receptor, melanin-concentrating hormone receptor 1 (MCHR1), and proopiomelanocortin (POMC) was also related to an increase in body mass index (BMI) and a higher risk of obesity, also modifying energy homeostasis in the offspring." (PMID 33042925, 2020). "A blockade of ciliogenesis in POMC-expressing cells from the mid-gestation led to severe obesity, indicating an importance of embryonic ciliogenesis of these cells for adulthood energy balance." (PMID 33188191, 2020). "In contrast, the induction of Xbp1s in POMC neurons protects against diet-induced obesity and improves leptin and insulin sensitivity." (PMID 32313051, 2020). "In conclusion, this study supports a role for POMC derived peptides in conferring protection from chronic HF diet related obesity in females through compensatory changes in the gut morphology and gut microbiota that collectively limit nutrient absorption." (PMID 33144604, 2020). "With POMC‐mediated leptin and insulin function playing a major role in the pathological development of obesity and MeS, the methylation status of POMC thus represents a pivotal therapeutic target." (PMID 31660128, 2019). "The major finding of this study shows that restoring POMC to excitatory ARC neurons fully restores obesity phenotype." (PMID 30957016, 2019). "A DBS neuromodulation approach of the ARC to treat obesity would preferably activate selectively the anorexigenic POMC and/or inactivate the orexigenic AgRP/NPY neurons." (PMID 31057350, 2019). "E2 activates POMC neurons, and E2 replacement in rodents prevents ovariectomized-induced obesity by decreasing food intake and increasing energy expenditure." (PMID 30997487, 2019). "Previously we observed that obesity induces microglial activation in close proximity to the anorexigenic proopiomelanocortin (POMC) neurons located in the arcuate nucleus of the hypothalamus." (PMID 31316470, 2019). "Mice with SOCS3 deletion either in the whole brain or in proopiomelanocortin (POMC) neurons (the key leptin target neurons in the arcuate nucleus of the hypothalamus) are resistant to high-fat diet-induced obesity." (PMID 31141984, 2019). "We identified six different novel variants within five obesity-related genes (SIM1, POMC, PCSK1, MC4R and LEPR) in seven out of 105 children with early-onset severe obesity in a Turkish population." (PMID 30991789, 2019). "The importance of POMC methylation status in obesity pathology cannot be overstated, with this locus being identified along with several other candidate genes in linking maternal nutrient exposure to adverse health in human intergenerational studies." (PMID 31660128, 2019). "It is also important to note that several age-related mechanisms impair POMC neuronal function and contribute to obesity." (PMID 31611548, 2019).
Obesity (continued). "Interestingly, Sirt1 expression was also shown to be affected by aging in the ARC, and it has been suggested that conditional knock-in of Sirt1 in AgRP and POMC neurons could protect against aging-associated obesity by inhibiting feeding and stimulating energy expenditure." (PMID 31309172, 2019). "POMC neuron-specific expression of Lepr reduces obesity in LeprloxTB/loxTB males starting at 13 weeks of age, plateauing at a ~10 g differential at 15–20 weeks of age8." (PMID 30824713, 2019). "Melanocortin peptides secreted from hypothalamic POMC neurons are anorexigenic and play a critical role in preventing obesity." (PMID 30957016, 2019). "The beta-catenin in the hypothalamus also affects NPY and POMC neurons, which suggests that the Wnt pathway regulates obesity by controlling food intake behaviour." (PMID 31540087, 2019). "Newly available, targetted drugs will offer a novel therapeutic option for those patients with monogenic obesity due to MC4R or POMC dysfunction." (PMID 30991789, 2019). "Another anti-obesity effects of ClpB can be mediated via its systemic and central actions, including direct activation of the anorexigenic proopiomelanocortin (POMC) neurons of the hypothalamic arcuate nucleus." (PMID 31878078, 2019). "This study points to a previously unappreciated role of ERAD in POMC neurons in prohormone maturation within the ER, by which it regulates feeding behavior, energy homeostasis, and obesity." (PMID 29457782, 2018). "Elevated TCPTP in POMC neurons in obesity and/or after fasting repressed insulin signaling, the activation of POMC neurons by insulin and the insulin-induced and POMC-mediated repression of HGP." (PMID 30230471, 2018). "We discuss the pathogenesis of this condition with emphasis on the crosstalk between hypothalamic and peripheral signals in the development of obesity and the POMC-melanocortin 4 receptors system as a target for therapeutic intervention." (PMID 28739551, 2018). "Further, conditional deletion of Rb1 in POMC neurons resulted in cell cycle reentry, neuronal apoptosis, and obesity; however, in contrast, deleting Rb1 in the antagonizing AgRP/NPY neurons was well tolerated." (PMID 30185666, 2018). "Nevertheless, our data reveal that the relatively small source of POMC specifically derived within the NTS is necessary for the obesity medication lorcaserin and the preclinical compound WAY161,503 to promote their full effects on feeding behavior." (PMID 30146485, 2018). "The leptin-induced protective mechanisms against obesity are dependent on SIRT1 in the POMC neurons." (PMID 30532738, 2018). "Obesity-induced damage to POMC neurons that ultimately decreases POMC neuron number was postulated to elicit hypothalamic inflammation." (PMID 30254630, 2018). "We have previously shown that POMC recovery at P25 completely prevents hyperphagia and obesity in arcPomc−/−:Cre mice." (PMID 30283405, 2018). "Expressing an unphosphorylable pRb nonselectively in the mediobasal hypothalamus or conditionally in anorexigenic POMC neurons inhibits diet-induced obesity." (PMID 30185666, 2018). "Based on these data we propose that there is potential to exploit the naturally occurring POMC-derived peptides to treat obesity but this relies on first understanding the specific function(s) for desacetyl-α-MSH and α-MSH." (PMID 29226825, 2018). "Taken together our findings are consistent with elevated TCPTP in obesity perturbing POMC insulin responses and the proportion of POMC neurons activated versus inhibited by insulin to drive HGP and fasting hyperglycemia in obesity." (PMID 30230471, 2018). "The treatment of obesity with EA, which was employed to reduce methylation Tsc1 and inhibit the activity of mTORC1, thereby controlling appetite-regulating factors (e.g., NPY, AgRP, and PoMC) and mitigating obesity." (PMID 29853949, 2018).